SIRT1 (sirtuin 1)
Diseases named in the same sentence as SIRT1 in open-access papers (continued):
Sharing a sentence is not in itself a finding about the gene and the disease.
endothelial dysfunction (continued). "It has been shown that SIRT1 prevents the development of endothelial dysfunction through attenuation progression of oxidative stress by multiple mechanisms including SIRT1/SOD, SIRT1/FOXO, SIRT1/eNOs, and SIRT1/NF-κB." (PMID 36580159, 2023). "A pharmacological activator of SIRT1, SRT1720, has been shown to extend mouse lifespan and healthspan and to reverse endothelial inflammation, ROS production, and endothelial dysfunction in aged mice." (PMID 37894840, 2023). "More selective action of SIRT1, blocking of NADPH oxidase activity reduce the inflammatory reactions and development of endothelial dysfunction in vascular aging." (PMID 36580159, 2023). "In the following paragraphs we will summarize the existing evidence about the pathophysiological role of SIRT1 in atherosclerotic cardiovascular disease (ASCVD), and in particular in one of its main functional features, namely endothelial dysfunction (ED)." (PMID 34690807, 2021). "In this review, we have discussed the specific molecular regulation of eNOS/SIRT1-related endothelial dysfunction and its contribution to CVD pathologies; furthermore, we selected nine different miRNAs that target the expression of eNOS and SIRT1 in CVDs." (PMID 33802566, 2021). "Despite its failure to rescue Sirt1 and eNOS, ectopic Skp2 expression significantly limited the increase of PAI-1 level, which is a crucial maker for endothelial dysfunction." (PMID 32313103, 2020). "For instance, resveratrol-mediated activation of SIRT1 inhibited the expression of NOX4 and the NADPH oxidative activity to reduce vascular superoxide production and to ameliorate endothelial dysfunction." (PMID 33304318, 2020). "Zarzuelo’ study indicated that impaired activity of SIRT1 up-regulated NADPH oxidase-derived ROS production and induced endothelial dysfunction in the vascular wall." (PMID 33308195, 2020). "It was confirmed that Sirt1 inhibition was engaged in upregulation of NOX oxidase subunits, p22phox, and NOX4, eventually leading to endothelial dysfunction due to O2− production." (PMID 28546854, 2017). "In contrast, elevation of Sirt1 levels and FOXO1 deacetylation via inhibition of miR-217 in ECs increases antioxidant effects and prevents endothelial dysfunction." (PMID 28546854, 2017). "To address this, we first measured aortic expression of Sirt1 and miR-204 in a high-fat diet (HFD) feeding model of endothelial dysfunction." (PMID 27586459, 2016). "It has been observed that overexpression of Sirt1 reduces expression of the Angiotensin II Type 1 Receptor (AT1R) and this inhibition seems to prevent endothelial dysfunction of cerebral arterioles." (PMID 24265619, 2013). "Sirtuin 1 (SIRT1) acts as a key regulator of vascular endothelial homeostasis, angiogenesis, and endothelial dysfunction." (PMID 23028940, 2012). "Sirtuin 1 (SIRT1), a key regulator of vascular NO production and vascular aging, is often downregulated under oxidative stress and inflammation conditions, contributing to endothelial dysfunction." (PMID 41374074, 2025). "Similarly, we observed significantly decreased levels of SIRT1 in senescent TSEC cells, accompanied by endothelial dysfunction delineated by markedly reduced eNOS, p‐eNOS, and intracellular NO levels." (PMID 39912563, 2025). "Recent studies explored the pivotal role of SIRT1 in mice lacking CR6-interacting factor (CRIF1), SIRT1 in mitochondrial dysfunction, and its potential as a treatment approach for endothelial dysfunction." (PMID 41567643, 2025). "In conclusion, we showed that the effect of ticagrelor related to the mitigation of endothelial dysfunction in stable CAD/COPD patients may be mediated, at least in part, by its capacity to increase SIRT1 and HES1 mRNAs levels." (PMID 32106619, 2020). "Therefore, enhancement of SIRT1 activity and SIRT1/AMPK axis upregulation inhibits oxidative injury, inducing endothelial dysfunction." (PMID 32848804, 2020).
endothelial dysfunction (continued). "Thus, the exact mechanisms of the SIRT1/FOXO1 pathway and its regulatory roles in endothelial dysfunction and angiogenesis should be analyzed under specific circumstances." (PMID 31068817, 2019). "Given this background and the known role of Sirt1 in endothelium-dependent vascular function, we explored if lack of Sirt1 downregulates Cav1 and produces endothelial dysfunction through induction of ER stress and miR-204." (PMID 28181559, 2017). "Lack of endothelial Sirt1 (eSirt1−/− mice) did not completely negate the effect of miR-204 inhibition on HFD-induced endothelial dysfunction, despite a marked decrease in aortic miR-204." (PMID 27586459, 2016). "One possibility is that the SRT2104 exposure achieved in this study did not lead to adequate or consistent SIRT1 activation, which would be required to reverse the vascular and endothelial dysfunction in these smokers." (PMID 23770971, 2013). "Therefore, caveoline-1 can be considered as a potential inhibitor of SIRT1, by the binding of the caveolin-1 scaffolding domain (CSD) to the caveolin-binding domain (CBD) of SIRT1, leading to reduced NO production, and, as a result, endothelial dysfunction." (PMID 34685718, 2021). "However, the relationship between miR-204 and Sirt1 in the context of endothelial dysfunction triggered by ER stress is not known." (PMID 28839162, 2017). "Thus, endothelial Sirt1 is a key but not the only target of miR-204 in HFD-induced endothelial dysfunction." (PMID 27586459, 2016). "Moreover, SIRT1 deacetylates FoxO proteins and thus stimulates FoxO-dependent antioxidative enzymes, such as catalase (CAT), manganese superoxide dismutase (MnSOD), and thioredoxin (TRX), eliminating ROS from endothelial cells and thus preventing endothelial dysfunction." (PMID 38003402, 2023). "In patients treated with ticagrelor or clopidogrel, we observed a negative correlation among changes in both SIRT1 and HES1 mRNA and serum levels of Epidermal Growth Factor (EGF), a marker of endothelial dysfunction found to be reduced by ticagrelor treatment in our previous study." (PMID 32106619, 2020).
prostate carcinoma (142 papers, 2008 to 2026). A carcinoma that arises from epithelial cells of the prostate gland. "In the present work, the underlying antitumor mechanism of Brassinin was explored in prostate cancer cells in association with glycolysis and the c-Myc/SIRT1/β-catenin signaling axis." (PMID 37762214, 2023). "Previous studies have shown that SIRT1, Notch1, c-Myc, and downstream targets of miR-34a are positively associated with prostate cancer stem cell traits." (PMID 37960146, 2023). "The introduction of a miR-34a precursor into paclitaxel and hormone-resistant prostate cancer cells caused a decrease of HuR, bcl-2, and SIRT1 expression and inhibition of the SIRT1 3′UTR activity." (PMID 23665903, 2013). "Furthermore, it has been revealed that SIRT1 expression is implicated in cell migration in prostate cancer and non-small-cell lung cancer." (PMID 39403142, 2024). "Thus, in the current study, the apoptotic mechanism of Brassinin was explored in prostate cancers in association with glycolysis-related proteins and the c-Myc/SIRT1/β-catenin signaling axis." (PMID 37762214, 2023). "A previous study reported that the loss of SIRT1 could delay Parkin translocation to the mitochondria and reduce mitophagy in the luminal epithelium in human prostate cancer." (PMID 37112536, 2023). "We envisage that ERG fusion-positive prostate cancer cells are susceptible to energy stress and the PGC1α-Sirt1 axis might provide survival benefits to tumors by activating antioxidant and metabolic functions of ERG fusion." (PMID 35508713, 2022). "However, SIRT1 has also been associated with survival and proliferation of tumors such as breast, gastric and prostate cancer." (PMID 25895126, 2015). "It has been shown that SIRT1 positive expression is strongly associated with tumorigenesis and tumor progression in various cancer types, such as colorectal cancer, gastric carcinoma, prostate cancer, lung cancer, and breast cancer." (PMID 25922660, 2014). "Interestingly, PML is frequently co-deleted with PTEN in metastatic prostate cancer, suggesting that PML loss could modulate PGC-1α in prostate cancer through SIRT1." (PMID 29629336, 2018). "Interestingly, our results differed from previous reports which indicated that SIRT1 serves as a positive regulator of epithelial-mesenchymal transition, the metastatic growth of prostate cancer cells, and is associated with malignancy in chronic myelogenous leukemia." (PMID 25424420, 2014). "Gain- and loss-of-function studies in human prostate cancer cells and mouse NEPC organoids confirmed that SIRT1 promotes NEPC, while pharmacological inhibition suppresses it." (PMID 42207152, 2026). "For example, SIRT1 enhanced replication and oncolytic efficacy of VSVΔM51 in prostate cancer cells (PCC)." (PMID 40927720, 2025). "A study demonstrated that SIRT1 levels directly influence the sensitivity of prostate cancer cells to VSV infection." (PMID 41294689, 2025). "Inhibiting or silencing SIRT1 also sensitizes prostate cancer cells to VSVΔM51, promoting viral replication and spread." (PMID 40927720, 2025). "Using prostate cancer cell lines with varying susceptibility to VSV-mediated killing, the researchers manipulated SIRT1 expression through genetic knockdown and pharmacologic inhibition." (PMID 41294689, 2025). "In prostate cancer cells, SIRT1/2 also promotes the multiubiquitination and proteasomal degradation of FoxO3 mediated by the E3 ubiquitin ligase subunit Skp2 by deacetylating FoxO3, thereby down‐regulating FoxO3 protein levels." (PMID 39778006, 2025). "Accumulating evidence evaluates SIRT1 suppression as an efficient mechanism for prostate cancer cell." (PMID 39796040, 2024).
prostate carcinoma (continued). "SIRT1, for example, fosters chemoresistance and castration-resistant prostate cancer through metabolic reprogramming, immune modulation, androgen receptor signaling, and enhanced DNA repair." (PMID 39796040, 2024). "For example, autophagy-induced SIRT1 degradation can enhance radiotherapy-mediated apoptosis in prostate cancer, showing its potential to reduce radio-resistance." (PMID 39403142, 2024). "Resveratrol, a naturally occurring polyphenol, has garnered attention for its ability to activate SIRT1 and its subsequent anti-cancer effects, particularly in cancers like breast and prostate cancer, where SIRT1’s tumor-suppressive role has been documented." (PMID 39403142, 2024). "Collectively, these findings indicate that SIRT1 is a key epigenetic modifier and regulator of the transcriptional machinery in prostate cancer." (PMID 39796040, 2024). "We also demonstrate the statistically significant down-regulation of DNA methyltransferases (COMT, MGMT, EHMT2, and SIRT1 deacetylase) in saffron-treated prostate cancer cells." (PMID 38201944, 2023). "In their previous research, Jung-Hynes demonstrated that SIRT1 inhibition precipitated significant antiproliferative effects in vitro on prostate cancer cells, attributed to a permissive increase in FOXO-1 acetylation and transcriptional activation." (PMID 37191417, 2023). "ZEB1 can also recruit the class III HDAC SIRT1 to silence E-cadherin and promote EMT and metastasis in prostate cancer cells, and the authors suggested the use of SIRT1 inhibitor as therapeutic strategy against metastasis cascade." (PMID 37369946, 2023). "They later found that melatonin demonstrated a level of SIRT1 inhibition comparable to that of nicotinamide and suramin (known inhibitors of SIRT1) and resulted in significant antiproliferation of numerous prostate cancer cell lines." (PMID 37191417, 2023). "Our current study exploited a novel therapeutic intervention targeting AXL, Notch1, Myc, or SIRT1 in an attempt to improve the management of androgen-refractory prostate cancers." (PMID 37960146, 2023). "Taken together, these results support further clinical studies on the therapeutic efficacy of cryopass-laser melatonin treatment in human tumors, and, in particular, on the therapeutic potential of inhibitors of SIRT1 toward prostate cancer." (PMID 37894275, 2023). "The authors further suggested that SIRT1 promotes the tumorigenesis of prostate cancer via SIRT1/S6K-mediated inhibition of autophagy." (PMID 36291902, 2022). "Taken together, these findings indicate a tumor suppressor role of miR-34a through the negative regulation of SIRT1 in prostate cancer." (PMID 36291902, 2022). "This suggests interesting crosstalks between these miRNAs and SIRT1 in prostate cancer, which needs to be explored in future studies." (PMID 36291902, 2022). "Since inhibition of SIRT1 has been reported to suppress prostate cancer growth, we silenced SIRT1 in VCaP cells to interrogate its role in ERG-PGC1α interaction." (PMID 35508713, 2022). "Conversely, androgen-independent prostate cancer cells, such as PC3 and DU145, have been shown to express higher levels of SIRT1 than androgen-dependent LNCaP prostate cancer cells." (PMID 36291902, 2022). "The current knowledge on the regulation of SIRT1–7 by miRNAs will be discussed in a subsequent section of this review, highlighting the consequences of this regulation in breast and prostate cancer." (PMID 36291902, 2022). "Nonetheless, animal studies are required to investigate how the tumor microenvironment of prostate cancer influences the outcome of SIRT1 activities in this regard." (PMID 36291902, 2022). "Several studies have shown that SIRT1 is highly expressed in prostate cancer, suggesting an important role for SIRT1 in its progression." (PMID 36291902, 2022).
prostate carcinoma (continued). "Other subsequent studies have also shown that certain miRNAs, whose expressions are downregulated in prostate cancer, act as tumor suppressors by negatively regulating SIRT1 via its 3′UTR." (PMID 36291902, 2022). "The tumor-promoting effects of SIRT1 in prostate cancer have been demonstrated through the regulation of EMT-related protein expression." (PMID 36291902, 2022). "In this regard, studies have investigated the effect of SIRT1 expression on AR, as a mechanism of SIRT1 in the development and progression of prostate cancer." (PMID 36291902, 2022). "SIRT1 has been shown to modulate catalytic protein activity as a part of its mechanisms of action in prostate cancer." (PMID 36291902, 2022). "Along this line, SIRT1 was upregulated in lung cancer, prostate cancer, and leukemia, and downregulated in colon tumors." (PMID 35458763, 2022). "This review discusses the current information on the tumor promotion or suppression roles of SIRT1–7 in breast and prostate cancers." (PMID 36291902, 2022). "miR-138-5p is known to regulate several pathological processes, such as myocardial injury, prostate cancer, intervertebral disc degeneration, among others, by targeting Sirt1 expression." (PMID 35302431, 2022). "Visfatin, along with SIRT1, is over-expressed in human prostate cancer and over-expression of visfatin increases prostate cancer cell resistance to oxidative stress." (PMID 33920379, 2021). "Previous research has showed that APS can inhibit lipid metabolism via miR-138-5p/SIRT1/SREBP1 pathways in prostate cancer and improve lipid metabolism disorders in diabetic hamsters." (PMID 33680062, 2021). "SIRT1 interfered with the prostate cancer cells making them permissive to the rVSV M Delta 51 infection." (PMID 34199429, 2021). "SIRT1 is involved in androgen-mediated transcriptional repression and growth suppression of prostate cancer cells." (PMID 34512726, 2021). "In prostate cancer cells, SIRT1 and ZEB1 simultaneously bind to CDH1, thereby silencing transcription, which results in metastasis." (PMID 34395273, 2021). "An increased expression of NNMT, in prostate cancer cells PC-3, stabilizes SIRT1 and contributes to cellular migratory potential and invasiveness, which can be overcome by exposure to an elevated level of SIRT1 inhibitor-NAM." (PMID 34073600, 2021). "Nevertheless, SIRT1 is upregulated in a range of cancers, including lymphomas, leukemia, and soft tissue sarcomas, prostate cancer, and lung and colon carcinomas." (PMID 32102511, 2020). "• Identification of theability of enoxacin to inhibitthe growth of prostate cancer cells through the reduction of HDAC1and SIRT1 protein levels by miRNA modulation." (PMID 32672457, 2020). "Melatonin considerably inhibits the expression and activity of Sirt1 protein in prostate cancer cells, which this is accompanied by a remarkable reduction in the proliferative activity of cancer cells." (PMID 32943992, 2020). "SIRT1 inhibited AR-dependent prostate cancer cell growth and induced endogenous AR target genes repression while SIRT1 antagonists induced expression of AR-responsive target genes (AR) both in vivo and in vitro." (PMID 33330467, 2020). "SIRT1 was significantly overexpressed in human prostate cancer cells, and SIRT1 inhibition contributes to suppress cancer cell growth." (PMID 31956359, 2020). "Numerous studies report Sirt1 as tumor promoter in several malignant cancers such as breast, colon and prostate cancer." (PMID 32727075, 2020). "Recently, the oncogenic function of SIRT1 has also been reported in cancer, including colon and prostate cancer." (PMID 31101119, 2019). "Sirtuin 1 is involved in aging, and in numerous types of cancer, such as prostate cancer, where ZEB1 recruits SIRT1 to the E-cadherin promoter." (PMID 30791369, 2019). "Such a relation highlights the possibility of SIRT1 as a promising target to preclude prostate cancer metastasis." (PMID 31817470, 2019).